TNF (tumor necrosis factor)
Diseases named in the same sentence as TNF in open-access papers (continued):
Sharing a sentence is not in itself a finding about the gene and the disease.
infection (continued). "To explore the possibility that cysteamine may control the increased production of inflammatory cytokines by BMDMs from CftrF508del/F508del mice following P. aeruginosa infection, we measured the levels of IL-1β and TNF-α in culture supernatants from BMDMs collected after 24 h following infection." (PMID 28079883, 2017). "Anti-TNF therapies neutralizing soluble and tmTNF have shown their efficacy for the treatment of autoimmune inflammatory diseases; however, the mechanisms by which TNF can control immune tolerance during infection and how this can be disrupted by TNF inhibition remains unclear." (PMID 28890718, 2017). "However iPPVO increased the mRNA expression of TNF-α after α-EHV infection compared to α-EHV alone." (PMID 28925977, 2017). "Data from studies of infection with L. monocytogenes in mice indicate that treatment with hLf displayed significant effects on one main organ target of this pathogen in regards to bacterial colonization, necrosis, and mRNA expression of pro-inflammatory cytokines TNFα, IL-1β and IFNγ." (PMID 28257033, 2017). "We investigated both the effects of TNFα neutralization early in the course of the disease and studied whether reactivation of an established infection would improve the reduction of the bacterial load in the tissue toward a more rapid and/or complete elimination of the infection." (PMID 28087648, 2017). "In EBOV-infected patients, fatal infection was associated with high levels of IL-10 and IL-1RA, modest levels of TNF-α and IL-6, and non-detectable levels of IL-1β, MIP-1α, and MIP-1β, while survivors were characterized by high levels of TNF-α, IL-1β, and IL-6 in plasma." (PMID 28861075, 2017). "Also, our findings of TNFα in mediating neutrophil MMP secretion have to be carefully interpreted in clinical care as there is a potential optimal concentration for host control of infection." (PMID 28173836, 2017). "Considering only our results of inflammatory profile in macrophages, strains such as CRL72, CRL1446, CRL352, CRL431, and CRL117 with a medium inflammatory profile could provide protection against the early stage of infection via Th1 with TNF-α and IL-6 production." (PMID 28348560, 2017). "On the other hand, the resistance to infection is associated with Th1 response, with the production of TNF, IL-12 and IFN-γ cytokines and induction of NOS2 expression with consequent NO production resulting in a M1 macrophage functional state, as observed in C57BL/6 mice infection." (PMID 29379478, 2017). "Thus, the immunosuppressive environment caused by in vivo neutralization of TNFα represents a persistent danger for the host once the infection is no longer controlled by antibiotics." (PMID 28087648, 2017). "All CD4+IFNγ-/- T cell recipients that finally succumbed to the infection continuously lost weight and developed a clinical score with similar kinetics or even a little earlier than control mice, whether treated with isotype or anti-TNFα antibody." (PMID 28222146, 2017). "Thus, TNF acts directly on BM CD4+ T cells to regulate their expansion following infection." (PMID 28671989, 2017). "In conclusion, our study found that host cytokine TNF-α could serve as an inducer to trigger egress of T. gondii from infected fibroblasts, suggesting a novel role of host inflammatory factors in intra-cellular pathogen infections." (PMID 29173277, 2017). "Hence, we quantified the expression of various immunity-related genes regulated by NF-κB: IFNß, CXCL2, TNF, CCL5 and CXCL10 in the brain of mice from two genetic backgrounds, at late stage of the infection by Tha or the isogenic Th4M virus mutated on the positions 77, 100, 104, 110 of the M protein." (PMID 29084252, 2017). "Thus, induction of PpiA mediated TNF-α by macrophages at the site of infection permits the multiplication of intracellular bacteria and may therefore present an evasion mechanism employed by M. tb." (PMID 28261567, 2017).
infection (continued). "Besides pulmonary infections, TNF-α was also essential for bacterial clearance in the spleen and liver of mice infected by intravenous injection of M. abscessus, reducing the lethality of the infection." (PMID 29163541, 2017). "TNFα might cause hyperexcitation in TMEV-infected mice by strengthening excitatory synapses via a TNFR1-mediated mechanism, whereas TNFR2 may provide anti-ictogenic effects during acute infection." (PMID 28497109, 2017). "Furthermore, MC-derived IL-6 and TNF-α in this phase of infection may contribute to granuloma maintenance." (PMID 29089945, 2017). "In addition, SseK proteins inhibit TNF-α-induced cell death during macrophage infection." (PMID 28069818, 2017). "Indeed, in TNF-deficient mice, which usually rapidly die after Mycobacterium bovis bacillus Calmette–Guérin (BCG) infection, the antimycobacterial immune response was restored by infection with a TNF-α-secreting recombinant M. bovis BCG, effectively protecting these highly susceptible mice." (PMID 29184553, 2017). "However, in vitro infection of AMs with a highly pathogenic strain of influenza A virus does not cause excessive TNF production." (PMID 28507549, 2017). "IFN-g and TNF-a present key roles in TB protection, and the Th1 subpopulation ofCD4+ T-cells secrete those cytokines that activate macrophages (Cooper 2009, Bold& Ernst 2012) and contribute to the migration of these cells to the siteof infection, particularly the lungs." (PMID 27074251, 2016). "However, it is slightly positively correlated with ECB around 100 days post infection, which may be attributed to chronically infected macrophages and T cell populations continual production of TNF during the dissemination scenario." (PMID 26913242, 2016). "TNF-α plays an important role in pathophysiology of many inflammatory disorders, whether due to infection or due to non-infectious causes." (PMID 28469676, 2016). "The subcutaneous injection of a high dose of L. major (4 × 106 promastigotes/50 μl nutrient broth medium/left hind paw) caused a significant increase in the levels of TNF-α, in the infected (left) and non-infected (right) hind paws at most time points of the experiment (till day 21 post-infection)." (PMID 26913003, 2016). "Early measures of circulating TNF-α/IL10 ratio may be a previously unidentified biomarker associated with burn injury severity and predictive of the risk of hypersusceptibility to repeated infections." (PMID 27761434, 2016). "Interestingly, the study also showed that pre‐incubation with OMVs prior to infection with whole cells inhibited the TNF‐⟨ responses, and increased the numbers of internalized B. abortus, demonstrating a role for OMVs in immunomodulation during or prior to subsequent infection." (PMID 27529760, 2016). "After trauma, the moderate secretion of TNF-α supports anti-infection processes and the repair of damaged tissue, while too much TNF-α or an improper balance of cytokines may lead to secondary inflammatory damage such as fever, shock or tissue organ hemorrhage and necrosis." (PMID 27123314, 2016). "In addition, TNFα directly effects immune cell recruitment by upregulation of endothelial adhesion molecules and induction of chemokine production which further recruit leukocytes to the site of infection." (PMID 26913029, 2016). "Therefore, while the amount of secreted TNF-α appears to be dependent on the infectious dose when cells are infected with virulent H37Rv, this does not appear to be the case when cells are infected with attenuated H37Ra infection." (PMID 27148227, 2016). "However, since TNF-α and IL-10 are major pro- and anti-inflammatory cytokines found to be involved in a variety of infections in animal and cell culture models, it is feasible that it plays a general role widely, rather than specifically toward select pathogens." (PMID 27761434, 2016).
infection (continued). "Therefore, during in vivo infection, Arg1 expression may be directly inhibited by type I IFN signaling and indirectly inhibited by type I IFN–dependent regulation of TNF and Th2-associated cytokine expression." (PMID 27849167, 2016). "However, flow cytometric analysis of TNF-producing cells in the cecal LP uncovered that the protein was not produced by NK cells but rather by cells from the myeloid compartment, at least at this early stage of the infection." (PMID 27341123, 2016). "Thus, the proposed high TNF-α expression as an indicator for the degree of infection in rainbow trout in another study may be counteracted by the spleen with a parallel elevation of IGF-I, although to a lesser extent." (PMID 26821056, 2016). "Moreover, IFN-γ-induced TNF and NO fuel astrocyte infection by T. cruzi." (PMID 27161638, 2016). "Interestingly, this sensitization may be unique to certain endothelial subtypes, as HDMEC, but not HLMEC or HUVEC, showed an increased permeability after DN-Csk infection and low-dose TNF-α treatment." (PMID 27603666, 2016). "Thus, inhibition of IL-6 production by F-4 would suggest an immuno-suppressive action, but its concomitant stimulatory effect on TNF-α, an important cytokine involved in the development of resistance to infection and cancer with roles in necrosis and apoptosis, suggests a more subtle mechanism." (PMID 27104574, 2016). "Unexpectedly, increased large intestinal IFN-γ and TNF concentrations could also be observed in commensal E. coli as compared to uninfected mice (p<0.001 and p<0.01, respectively), whereas only colonic TNF was lower 6 days following E. coli versus CCUG 30485 strain infection (p<0.05)." (PMID 27438014, 2016). "However, the IL-6, TNF-α, and IL-12p70 levels induced by either ΔsspA-1 or ΔvirD4–89K were markedly lower than those induced by the wild-type strain, particularly at 8 h after infection." (PMID 27270879, 2016). "Thus, the strong association of IL-6 with disease severity and death might be explained in two steps: firstly, through the inhibition of TNF-α in the early phase of infection, and later, by its inhibitory effect on Th1 responses." (PMID 26814478, 2016). "Of those, only TNF-α and IL-10 had negative associations with infection status." (PMID 27418744, 2016). "Moreover, on the one hand, TNF-α stimulates the macrophages during the early response to infection, but on the other hand, macrophage activation, especially the maturation of blood monocytes to tissue macrophages, causes an increase in the replication of viruses within these cells." (PMID 27399757, 2016). "However, reduction in the systemic TNFα response was imminent with each successive re-infection." (PMID 26981777, 2016). "Anti-TNF IgG was employed to investigate whether TNFα-mediated infection induced HSPC mobilisation." (PMID 27306736, 2016). "Thus, given our study design, we expect that our results on the association of TNF-α/IL10 cytokine ratio are predictive of later infections, rather than a consequence of pathogenic encounter." (PMID 27761434, 2016). "Besides chemokines, cytokines such as TNF-α are released acutely in response to injury or infection, and function to initiate and maintain the inflammatory process in part by stimulating other pro-inflammatory cytokines (e.g., IL-1α, IL-1β, and IL-6) and chemokines (e.g., CCL2, CCL3, and CXCL2)." (PMID 26860080, 2016). "Therefore, we tested whether IFNγ directly enhanced astrocytes infection by T. cruzi or whether this effect depends on TNF induction." (PMID 25695249, 2015). "This was associated with increased production of disease-exacerbating proinflammatory cytokines (IFN-γ, IL-16 and TNF-α), impaired production of parasite-specific IgG, IgG1 and IgG2a antibodies and failure to sustain strong germinal centre responses during the chronic phase of infection." (PMID 25875604, 2015).
infection (continued). "To investigate how IL-33 might interfer with the host immune response, we measured the levels of the key Th1 cytokines (IFN-γ, IL-12 and TNF-α), key Th2 cytokines (IL-4, IL-5 and IL-13), and the regulatory cytokine IL-10 in the serum at various time-points after infection with PbA." (PMID 25659095, 2015). "Indeed, anti-TNF completely prevented the IFNγ-enhanced infection of astrocytes by T. cruzi." (PMID 25695249, 2015). "Additionally, serum TNF levels correlate with the severity of infections." (PMID 25762127, 2015). "Interestingly, TNFα production after infection showed species-specific differences." (PMID 29470790, 2015). "Therefore, it is possible that the reduction in TNF expression observed during FV1 lpg1− infection may also be IRF8-specific." (PMID 26630499, 2015). "On the other hand, increased production of IL-22 and TNF-α could not only promote tissue homeostasis in inflammatory diseases, but also regulate host defense by inducing antimicrobial peptide production at epithelial barriers in infections." (PMID 26107738, 2015). "However, while cellular levels reached maximum at 2 weeks post-infection and were sustained at 3 weeks post-infection in TNFf/f and NsTNF−/− mice, TNF−/− mice displayed significantly higher levels at 2 weeks post-infection, the differential levels enhancing even further at 3 weeks post-infection." (PMID 26112704, 2015). "Additionally, infection by schistosomes reduces tumor necrosis factor α (TNFα) production in BCR-stimulated MemB subsets, and this might contribute to decreased pathogen-specific Th1 responses." (PMID 25884828, 2015). "We speculated that early production of IFN-γ during infection probably arises from NK cells, whereas TNF-α functions relatively late in the inflammatory cycle induced by infection, at a time when virus is already being contained and the response is centered on resolution of the inflammation." (PMID 25888728, 2015). "In the current study, we hypothesized that F. tularensis polarizes antigen presenting cells during the early stages of infection towards an anti-inflammatory status characterized by increased synthesis of IL-10 and decreased production of IL-12p70 and TNF-α in an IFN-ɣ-dependent fashion." (PMID 26114641, 2015). "In order to determine whether appropriate memory responses were generated in the VLP-treated CD4+, CD8+, IFN-gamma, or TNF alpha knockout (or antibody depleted) mice that survived infection, these mice were re-challenged with EBOV >28 days later, without additional VLP treatment." (PMID 25785602, 2015). "The splenocytes of vaccinated hamsters receiving liposomal rCPC and cocktail of three liposomal CPs showed higher IFN-γ, IL-2, TNF-α and IL-12 mRNA expression than all other groups but appreciable downregulation of macrophage deactivating cytokines like IL-4, IL-10 mRNAs, before and after infection." (PMID 25144181, 2014). "Although that study did not indicate whether these were primary or secondary infections, low levels of TNF-α appear to be associated with disease severity during Leishmania infection." (PMID 25295285, 2014). "A continuous and high level of TNF-α could hint at a poor prognosis of severe infection." (PMID 27602373, 2014). "However, it was recently suggested in a model of infection caused by vaccinia virus inoculation in C57BL/6 mice that F4/80+Ly6G+ cells are indeed monocytes with a great capacity of producing ROS and IFNγ whilst Ly6G− monocytes produce NO and TNFα." (PMID 25242870, 2014). "This is supported by the reduction of IFN-γ and TNF-α production at the end of the acute (14th days) and beginning of the chronic stage (21st days) of the infection, suggesting a resolution of the inflammatory reaction in TR mice that survived the acute phase of the infection." (PMID 25437299, 2014). "Interestingly, TNF-deficient mice failed to accumulate macrophages at the infection site whereas the infiltration of neutrophils was not impaired." (PMID 25325020, 2014).
infection (continued). "Furthermore, the authors demonstrated that the expression of complement components, receptors and regulators is differentially regulated by lipopolysaccharide and by other TNF-α-, IL-1- or prostaglandin E2-related inflammatory stimuli, conditions mimicking infection and tissue inflammation." (PMID 25061945, 2014). "Furthermore, not only local, but even systemic immune responses were less pronounced upon ΔhtrA mutant infection as indicated by significant lower serum levels of pro-inflammatory cytokines such as TNF-α and IL-6 in ΔhtrA mutant as compared to WT strain infected mice." (PMID 24959425, 2014). "IL-6 and TNF-α production upon Lae 303 and 327 infection was less than that observed for L. guyanensis, which might be attributable to the lower LRV load in the L. aethiopica strains and/or because of a higher parasite survival rate in the case of L. aethiopica." (PMID 24762979, 2014). "Thus, to mimic more closely the conditions under which neutrophils in vivo would generate NETs, we exposed neutrophils to tumour necrosis factor-alpha (TNF-α), a pro-inflammatory cytokine whose levels are increased during infection and in inflammatory states, prior to stimulation with IL-8 or LPS." (PMID 24779584, 2014). "Infection of monocytes and monocyte-derived DCs with chlamydial serovars Ba, D and L2 could induce detectable secretion of cytokines IL-8, IL-6, IL-1β, IL-10 and TNF." (PMID 25123797, 2014). "Our results suggest that the F1 domain, which contains the highest affinity epitope of the NH36 for CD8+ T cells, might be important for the development of CD8+ TCM cells, which through the high secretion of IL-2, or TNF or IL-2-TNF actively contribute to the cure of the established infection." (PMID 24966857, 2014). "Therefore, we next investigated whether infection with B. anthracis spores induced the expression of TNF-α." (PMID 25472474, 2014). "In placebo-controlled trials evaluating each one of three TNFα blockers for RA patients, the rate of any infections did not exceed the rate in the placebo group, while data from a meta-analysis suggest an increased risk for serious infections." (PMID 24655394, 2014). "In addition, Mtb HN878 infection also inhibits the production of TNF-α in macrophages, suggesting that the increased virulence of Mtb HN878 infection may be due to the reduced generation of Th1 responses and impaired macrophage activation in the host." (PMID 24831696, 2014). "Similarly, rapid intracellular macrophage growth rates by strains of M. tuberculosis strains correlated with rapid production of IL10 that antagonizes the proinflammatory response by down-regulating the production of TNFα in THP-1 cells during the early stages of infection." (PMID 25111300, 2014). "Our findings suggest that a balance of TNF-α and IL-10 defines a granuloma environment that may be beneficial for both host and pathogen, but perturbing the balance could be used as a novel therapeutic strategy to modulate infection outcomes." (PMID 23869227, 2013). "Whether TNF-α alters erythropoiesis early in the infection needs to be examined." (PMID 23533629, 2013). "However, infection of macrophages by smooth M. abscessus resulted in minimal release of TNFα." (PMID 23451220, 2013). "Although TNF secretion by infected SOCS3-deficient macrophages is reduced, TNF expression in the lungs of M. tuberculosis-infected Socs3fl/fl LysM cre mice was not diminished, suggesting that a role for TNF in the susceptibility to infection of Socs3fl/fl LysM cre mice is unlikely." (PMID 23853585, 2013). "Moreover, infection with ΔsseL mutant bacteria did not cause macrophages to secrete more TNF-α (at 10 h post-uptake) and Il-1β (at 24 h post-uptake) when compared to macrophages infected with the wt strain." (PMID 23308136, 2013).